IL4 (interleukin 4)
Diseases named in the same sentence as IL4 in open-access papers (continued):
Sharing a sentence is not in itself a finding about the gene and the disease.
viral infection (continued). "In total, these data provide strong evidence that SIGNR3 upregulation is a key component of the IL-4/IL-13-mediated increase in virus infection in murine macrophages." (PMID 31825972, 2019). "The CD4+IL-4+ cytokine response following KOS virus infection was elevated on day 14 PI, compared to D22 (ICP22 null) virus infection (21.6% vs. 6.9%, P < 0.001), but differences between these groups were not significant on day 28 PI (3.9% vs. 10%, P > 0.05)." (PMID 31387116, 2019). "While the impact of IL-4/IL-13 upregulation of mannose-binding CLRs such as SIGNR3 on virus infection of pmacs is statistically significant, it is a modest effect." (PMID 31825972, 2019). "In moderate-to-severe persistent asthmatics, viral infection was associated with increased protein abundance of CXCL10, IL-4, sICAM-1, CCL2, CCL20 and CCL24." (PMID 30463560, 2018). "In various infectious, diseases such as leishmaniasis, trypanosomiasis and viral infection, are concordance with IL-4 as well as IL-10 production (as Th2 cytokines) and L-Arg increased catabolism in M2 macrophages." (PMID 29253854, 2017). "With regard to CD80 expression, M0 and M(LPS + IFN-γ) cells increased surface levels following viral infection, while M(IL-4) cells expression of CD80 remained largely unchanged (column 1)." (PMID 29250063, 2017). "CD1d-recruited iNKT cells rapidly produce large amounts of Th1 and Th2 cytokines, including gamma interferon (IFN-γ), interleukin-4 (IL-4), IL-10 and IL-13, which protect against viral infections and cancers." (PMID 25885042, 2015). "Here, we show that IL-4-induced innate CD8+ T cells are able to effectively control chronic virus infection." (PMID 26452143, 2015). "Here we found that these IL-4-induced innate CD8+ T cells are critical for accelerating the control of chronic virus infection." (PMID 26452143, 2015). "The vIFN-γbp had minimal impact on CTL activity in WT, IL-4−/− and IL-4Rα−/− mice as these strains generated comparable responses to WT or mutant virus infection." (PMID 25751266, 2015). "Although microglia only seem to express DC-SIGN in low levels after induction via IL-4 and GM-CNS and LPS (approximately 100-fold lower than in monocytes), they do express a number of HSPGs that are thought to facilitate viral infection." (PMID 25706756, 2015). "In this study we demonstrated that IL-4-induced innate CD8+ T cells are able to effectively control the chronic viral infection." (PMID 26452143, 2015). "We found that IL-4-induced innate CD8+ T cells immediately accumulated after viral infection and produced a robust amount of effector cytokines." (PMID 26452143, 2015). "Flow cytometric analysis revealed that WT virus infection increased GzB+ NK cell (CD3-DX5+) numbers in IL-4−/− and STAT-6−/− mice compared to WT mice." (PMID 25751266, 2015). "We found that proinflammatory cytokine (IL-5, IL-4, and IL-6) production was significantly increased later in the P17 (MA) viral infection process (at 5 dpi) compared with the parent (P0) virus infection." (PMID 26526113, 2015). "In HIV, it has been reported that viral infection induced FcepsilonRI+ hematopoietic cells to produce IL-4, which inactivated the host adaptive immune response." (PMID 24358317, 2013). "Data indicate that the amount of IL-4 available during virus infection can regulate the expression of IL-4Rα on CD8+ T cells in a STAT6 dependent manner." (PMID 23383283, 2013). "Cytokines and chemokines that showed limited response in mice with any viral infection included Eotaxin, GM-CSF, IL-1α, M-CSF, IL-2, IL-3, IL-4, IL-5, IL-7, IL-9, IL-12p40, IL-13, IL-15, IL-17, MIP2, LIX, MIP1β, RANTES, IL-12p70, and VEGF (data not shown)." (PMID 23441208, 2013). "Together, the behavior of these genes is consistent with an upregulation of immunosuppressive signals, compounded by the lack of factors that lead to the development of adaptive immune response such as production of IL2 and IL4 following virus infection." (PMID 23638192, 2013).
viral infection (continued). "Our results clearly indicated that amongst the different IL-4/IL-13 receptor components only cell surface IL-4Rα expression was significantly down-regulated on activated CD8+ T cells following virus infection." (PMID 23383283, 2013). "The clearance of influenza relies on the production by multiple cells of anti-viral type I interferons and Th1 cytokines, while the Th2 cytokine IL-4, delays the recovery from viral infection." (PMID 21092162, 2010). "As we were interested in airway responses of CD8+ T in the context of viral infection, we then investigated whether levels of expression of surface antigens associated with activation, adhesion and transmigration capabilities were altered by the presence of IL-4 during CD8+ T cell stimulation." (PMID 16001979, 2005). "In the microenvironment of small airway epithelial cells, particularly during viral infections, the presence of IL-4 or IL-13 may enhance the expression of TSLP and IL-8." (PMID 41576028, 2026). "Within the microenvironment of small airway epithelial cells, particularly during viral infections, the presence of IL-4 or IL-13 may augment the expression of TSLP and IL-8." (PMID 41576028, 2026). "Although IL-4 and IL-13 are predominantly produced by Th2 cells, epithelial cells may also release these cytokines in response to dsRNA or viral infection." (PMID 41576028, 2026). "The cytokine analysis results showed that a PRV infection could increase the levels of TNF-α, IFN-γ and IL-6 and reduce the level of IL-4 to regulate the body’s immune response to a virus infection." (PMID 37508153, 2023). "In this study, we investigated whether exogenous IL-4 could enhance the immune response to a viral infection." (PMID 38037190, 2023). "Therefore, the GRb1/IL-4@CS/CaP delivery system can potentially trigger specific immune responses against infectious and viral diseases." (PMID 35878372, 2022). "Analysis of viral infection at 24-hours post-infection (hpi) showed an even higher reduction in viral RNA levels upon IL-4 treatment, which may be due to anti-viral activities of IL-4 that occur at later steps in infection." (PMID 34097709, 2021). "As one of the important anti-inflammatory factors, IL-4 can help fight viral infections." (PMID 34275451, 2021). "This may explain why elevated serum IL-4 can be detected following certain parasitic, helminthic and viral infections, including SARS-CoV-214,46–51." (PMID 34006897, 2021). "Interestingly, TCs in the ACR patients expressed high levels of IL-4, which was predicted to bind IL-4R and IL-2R in TC-MC interactions and was reported to enhance viral infection." (PMID 32780218, 2020). "The blocking of type 2 inflammation by therapeutic antibodies against IgE, IL-5, or the IL-5 or IL-4/-13 receptors has so far not been suspected to increase the risk of viral infections." (PMID 32915172, 2020). "IL-4 can be induced in both synthetic peptides and virus infection groups." (PMID 33375108, 2020). "On the other hand, IL-4 can also inhibit viral infections by promoting innate immunity." (PMID 32915172, 2020). "However, as TIM-4 expression was not enhanced by IL-4/IL-13 treatment, this receptor cannot be responsible for the increase in virus infection mediated by IL-4/IL-13." (PMID 31825972, 2019). "Interestingly, the ability of B cells to increase their respiratory capacity after viral infection requires early IL-4 production because the upregulation of the OCR is diminished when the early IL-4 wave is inhibited." (PMID 29249358, 2018). "Therefore, our results indicate that the production of IL-4 by NKT cells immediately after viral infection contributes to a pre-TfH IL-4 wave at the follicular borders that facilitates the initial seeding of germinal center cells." (PMID 29249358, 2018). "Finally, it has been demonstrated that in allergic patients, molecules of the allergic cascade (IL-4, IL-13, IgE receptor) are directly triggered and up-regulated by viral infections of the lower airways." (PMID 31826034, 2018).
viral infection (continued). "Early viral infections of the lower airways lead to a further intensification of the allergic immune reaction and in particular to an expression of the IgE receptor, which further heats up the Th2 cascade (“Il-4/IL-13 storm”)." (PMID 31826034, 2018). "Established cultures of infected cells maintained this phenotype, while parallel mock-infected cultures switched immunoglobulin heavy chain isotype usage, a likely consequence of continuous CD40 ligand and IL-4 stimulation, suggesting that virus infection suppresses isotype switching." (PMID 26819313, 2016). "It is possible that IL–4 deficiency probably has effects not only on the loss of the IL-4-induced innate CD8+ T cells but also on the development of antibody responses, an important component in determining the outcome of virus infection." (PMID 26452143, 2015). "Thereby, IL-4-induced innate CD8+ T cells provide an effective barrier to the establishment of persistent infection via effective virus control during the early phase of viral infection." (PMID 26452143, 2015). "Furthermore, IL4/7-grown VSTs have been tested in two clinical trials and were successfully able to resolve viral infections after HSCT." (PMID 25734008, 2015). "This hypothesis is supported by the observation in mice that elevation of IL-4 levels concurrent with viral infections suppresses or delays activation of virus-specific CD8+ T cells and leads to delayed viral clearance." (PMID 16001979, 2005). "These insights may help uncover the molecular basis for specific T and B cell immune outcomes under different viral infections and vaccinations, as well as inform rational vaccination design and therapies for diseases underpinned by IL-4/IL-13 dysregulation (e.g. asthma and some cancers)." (PMID 34006897, 2021). "However, IL-4 has a dual role in viral infections due to two different haplotypes in the IL-4 gene." (PMID 32915172, 2020). "For example, blockade of IL-4 signal pathway may be a novel strategy to control viral infections." (PMID 30781810, 2019). "Furthermore, these studies also implied the possibility that the efficacy of kinds of viral infection and viral-based vector might be regulated by IL-4 administration." (PMID 30781810, 2019). "Interestingly, this phenomenon seems to be conserved upon viral infection in other species because our transcriptomic analysis of Zika-virus-infected macaques revealed a positive correlation between early NKT cell-IL-4 gene signatures and the serum levels of Zika virus-neutralizing antibodies." (PMID 29249358, 2018). "High levels of IL-4 secretion could further stimulate the activation of B cells to enhance the antigen presenting ability, and produce higher antibody titre to neutralize the virus infection." (PMID 28786949, 2017). "Viral infection or stimulation with dsRNA can upregulate TSLP expression, an effect that is further amplified in the presence of IL-4 or IL-13." (PMID 41576028, 2026). "ST3GAL2 resists viral infection by downregulating pro-inflammatory cytokines (IL-6, IL-18, IL-1β, IFN-β, TNF-α) and upregulating anti-inflammatory cytokines (IL-4, IL-10, IL-13)." (PMID 40755778, 2025). "The low antibody titers for unadjuvanted QIV correlated well with low T-cell responses (IL-4 and IFN-γ ELIspots) as well as inadequate protection against virus infection, implied by high levels of replicating virus in lungs upon intranasal IVR-180 challenge." (PMID 38711520, 2024). "Immune activation against viral infections involves the typical responses of specific cytokines such as IFN-γ, IL-2, and IL-4." (PMID 39507777, 2024). "The immune response to viral infection included an increase in IFN-γ and IL-17 and a decrease in IL-4 and IL-13." (PMID 36768715, 2023). "To further investigate the Th1/Th2 balance in airways of asthmatics during viral infection, we analyzed the ratios of IFN-γ/IL-4 and IFN-γ/IL-5 cytokines." (PMID 37865742, 2023).
viral infection (continued). "In the case of viral infections, elevated levels of various inflammatory cytokines, including IL-1β, IL-6, IL-7, IL-17, IFN-γ, IL-8, TNFα, and GM-CSF are observed, alongside IL-4 and IL-5." (PMID 37692890, 2023). "Emodin was able to combat viral infection by regulating the levels of the cytokines TNF-α, IFN-γ, IL-6, and IL-4 in the sera of infected mice." (PMID 37764342, 2023). "In the course of viral infection, Th2 CD4+ T cells promote the humoral immune response by secreting IL-4, IL-5, IL-10 and other Th2 cytokines." (PMID 35100303, 2022). "The increase in IL-1β, IL-6, IL-4, and TNF-α expression in the spleen indicates the activation of the immune system, resulting in resistance to virus and prevention of virus infection." (PMID 36177044, 2022). "Both IL-4 and IFN-γ were shown to downregulate the expression of SARS coronavirus receptor angiotensin-converting enzyme 2 (ACE2), in order to inhibit viral infection." (PMID 34307393, 2021). "The remaining 20 non-targetable SARS-CoV-associated disease genes include proteins (e.g., CD14, IFNA1, IFNB1, IL4, IL10, CCL5) having key roles in the immune-inflammatory response to viral infection as well." (PMID 33544720, 2021). "At the same time, IL-1β, IL-4, IL-6, IFN-γ, GM-CSF, and TNF-α activate inflammatory effector mechanisms typical of a viral infection." (PMID 34831403, 2021). "Since T lymphocytes (CD8+) play an important role in the fight against viral infection, ICS was used to assess IL-4 and IFN-γ cytokine production in T lymphocytes (CD8+)." (PMID 32118075, 2020). "Two murine DC-SIGN-like family members, SIGNR3 and SIGNR5, were upregulated by IL-4/IL-13 in murine macrophages, but only SIGNR3 enhanced virus infection in a mannan-inhibited manner, suggesting that murine SIGNR3 plays a similar role to human DC-SIGN." (PMID 31825972, 2019). "Enhanced IL-4/IL-13-mediated infection was blocked by mannan, indicating that mannose-binding CLRs, such as DC-SIGN, are responsible for the increased virus infection." (PMID 31825972, 2019). "For FEV1, statistically significant interactions between viral infection and inflammation were seen for CXCL10 and TLR3 mRNA, IL-4 and CCL24 levels." (PMID 30463560, 2018). "In conclusion, our data support a model wherein a pre-TfH wave of IL-4 secreted by interfollicular NKT cells triggers the seeding of germinal center cells and serves as an innate link between viral infection and B cell immunity." (PMID 29249358, 2018). "For FVC, statistically significant interactions between viral infection and inflammation were seen for CXCL10 mRNA, TLR3 mRNA, IL-4, IL-13, CCL5, CCL20 and CCL24." (PMID 30463560, 2018). "Our results show that, during the initial stages of a viral infection, NKT cells become the main source of IL-4 in draining lymph nodes." (PMID 29249358, 2018). "In RSV-infected mice and cotton rats, AS1411 administration was associated with decreased airway inflammation and with decreased IL-4/IFN-γ ratios, both of which are considered to reflect a beneficial host response to virus infection." (PMID 28925950, 2017). "Taken together, these data suggest that a high level of Eomes expression allows IL-4-induced innate CD8+ T cells to exhibit their prompt and significant effector function, thereby controlling viremia during the early phase of virus infection." (PMID 26452143, 2015). "IL-4 also decreased the IFN response and increased permissiveness to viral infection of cDCs exposed to a HIV-based lentivirus." (PMID 24489947, 2014). "Using a HIV-derived lentivirus infection model, we also show that IL-4 decreases DC production of Type I IFN and IFN-responsive genes (IRGs) and increases the permissiveness of DCs to viral infection." (PMID 24489947, 2014). "With the hope of understanding how interleukin (IL)-4 and IL-13 modulated quality of anti-viral CD8+ T cells, we evaluated the expression of receptors for these cytokines following a range of viral infections (e.g. pox viruses and influenza virus)." (PMID 23383283, 2013).